MPO (myeloperoxidase)
Diseases named in the same sentence as MPO in open-access papers (continued):
Sharing a sentence is not in itself a finding about the gene and the disease.
infection (continued). "Formation of NETs results in extrusion of nuclear and mitochondrial DNA mixed with granular and some cytoplasmic constituents, as neutrophil elastase (NE), myeloperoxidase (MPO), and the citrullination of histone H3 (CitH3), in response to infection or cancer burden." (PMID 32226771, 2020). "The aim of the study was to evaluate the dynamics of myeloperoxidase (MPO) and lysozyme (LZM) in the experimental infection of rabbits with the Lagovirus europaeus/GI.1a virus, which is a pathogen causing high mortality, decimating rabbit farms all over the world in a short time." (PMID 32899838, 2020). "A smaller number of inflammatory monocytes and mo-DCs also became MPO+ during the first 24 hr, suggesting that these cells can contribute to the capture of apoptotic neutrophils, although their infection levels were not reduced by neutrophil depletion." (PMID 33137149, 2020). "Myeloperoxidase (MPO), a marker of neutrophil activity in intestinal mucosa, and lipocalin-2 (LCN-2), a glycoprotein upregulated in tissue damage under infection conditions, have been considered as biomarkers of environmental enteric dysfunction, including EPEC infection in children." (PMID 33392105, 2020). "The increase in MPO and EPO as an indirect measurement of neutrophils and eosinophils in the intestine of WT mice might contribute to the establishment of infection." (PMID 32353980, 2020). "We also saw no major change in MPO gene expression levels in the AGMs at any time during infection, supporting the lack of sustained alteration to neutrophil populations in response to SIV infection in AGMs." (PMID 32119719, 2020). "G-1-treated female mice also had reduced levels of the inflammatory cytokine TNFα at the site of infection, with no significant reduction in levels of the other cytokines tested or MPO compared to vehicle-treated mice." (PMID 30718654, 2019). "Firstly, granulocytes from Tacrolimus pre-treated mice were less efficient in phagocytizing E. coli; secondly, they produced less MPO upon stimulation with E. coli; lastly, the chemokine receptor CXCR2 was markedly decreased in circulating granulocytes in the early hours of infections." (PMID 30643171, 2019). "This confirms that expression of the lyz:MPO-mEmerald transgene does not interfere with neutrophil recruitment to sites of infection." (PMID 31002727, 2019). "Using a combination of approaches for studying neutrophil migration, we found that expression of the lyz:MPO-mEmerald transgene does not interfere with neutrophil recruitment to sites of infection and inflammation." (PMID 31002727, 2019). "The level of MPO, a marker of neutrophil infiltration during inflammation, was not significantly affected by infection or pretreatment with ZS2058 or T, but was significantly reduced by LGG." (PMID 30842764, 2019). "Infection with Candida albicans in myeloperoxidase lacking zebrafish led to a failure in the removal of the pathogen." (PMID 31040570, 2019). "Compared to infection with WT Bacillus, infection with a strain lacking the S-layer protein SlpA resulted in significantly less MPO and less PMN infiltration in infected mouse eyes." (PMID 31703354, 2019). "Lastly, by accessing the levels of MPO-DNA complex on the acutely CHIKV-infected patients, we found a correlation between the levels of NETs and the viral load in the blood, suggesting that NETs are also released in natural human infection cases." (PMID 32082301, 2019). "The reduction in MPO activity greatly supports the antimicrobial and wound healing activities of Rhus coriaria fruits (AERc) against infection of skin wound tissues with gram-positive and gram-negative bacteria." (PMID 31379964, 2019). "L. amazonensis infection also increased the levels of TNF-α and IL-1β, and MPO activity in the ipsilateral, but not contralateral paw tissue of infected mice when compared to control non-infected animals at day 40 after the infection (p < 0.05)." (PMID 31138231, 2019).
infection (continued). "We report here that myeloperoxidase activity is not necessary to fight the infection in our experimental system." (PMID 30016370, 2018). "On the other hand, the infection did not modify the MPO activity in the jejunum and ileum of the rats (p > 0.05)." (PMID 29324806, 2018). "In addition, infection with a cell line that overexpressed ISP2, WT (pXG-ISP2), demonstrated that an excess of ISP2 delayed MPO-specific bioluminescence, which increased only from 4 wk compared with 2 wk during WT and Δisp2/3 infection." (PMID 29097502, 2018). "Further, MPO mRNA was not induced due to infection or LPS-stimulation in wild-type, gp91phox−/− or iNOS−/− cells." (PMID 28697801, 2017). "Administration of TFSD post PCV2 infection was able to promote the activity of XOD and MPO." (PMID 28819143, 2017). "The activities of the enzymes MPO and NAG were significantly (p < 0.05) increased in lungs of mice infected with IAV compared with NI mice, suggesting that neutrophils and macrophages, respectively, had been recruited to the site of infection." (PMID 29018774, 2017). "Neither infection nor LPS-stimulation led to a significant induction of gp91phox mRNA in wild-type, MPO−/− or iNOS−/− Hoxb8 neutrophils." (PMID 28697801, 2017). "As was observed in infected humanized NSG mice, there was a transient increase in MPO at 3 h but not at 24 h post-infection in NSG mice adoptively transferred with human PMN." (PMID 26618545, 2015). "5-LO−/− mice had a similar increase of MPO activity 24 h after infection but, unlike WT mice, there was higher MPO activity 72 h after infection." (PMID 23991239, 2013). "In the absence of infection there are detectable levels of nitrotyrosine in neutrophils, likely due to myeloperoxidase activity, an enzyme that is neutrophil-specific in zebrafish." (PMID 24367256, 2013). "MPO induction increased throughout the infection in WT mice (p<0.05 between D15 and D60) but not in Jα18-/- mice." (PMID 22457760, 2012). "To investigate neutrophil - DCs interactions following injection of the parasite directly, we evaluated dermal DCs recovered from C57BL/6 mice 24 hr after infection with Lm-RFP parasites, and stained for neutrophil derived-myeloperoxidase (MPO) and elastase (NE)." (PMID 22359507, 2012). "Secondly, when the infections were initiated by RFP L. major metacyclics, the majority of the RFP+ DCs recovered from the injection site at 24 hr also stained positive for neutrophil-derived MPO and elastase." (PMID 22359507, 2012). "Vaccinated and non-vaccinated dogsexhibited no detectable level of MPO activity before challenge infection." (PMID 21625470, 2011). "NO level and MPO activity were significantly (P < 0.05) increased in spleen by 195.49% and 190.94%, respectively, due to VRSA infection as compared to control group, in which they were significantly (P < 0.05) decreased by 37.03% and 44.76% due to treatment of nanoconjugated vancomycin." (PMID 21785683, 2011). "In line with their similar histopathology and Ly-6G scores, pulmonary MPO concentrations, indicative for the number of neutrophils in lung tissue, were similar in WT, heterozygous and homozygous FVL mice at both 24 and 48 hours after infection." (PMID 20682036, 2010). "To isolate the impact on MPO levels of vaccination, and not severity of infection, we adjusted absolute MPO levels in individually marked organs for the fungal or bacterial burden in those individual organs." (PMID 20041174, 2009). "In related experiments, the co-recruitment of both macrophages and neutrophils to sites of infection was verified using transgenic zebrafish embryos (Tg(mpo::GFP),) that express GFP under control of a neutrophil-specific myeloperoxidase (MPO) promoter (for example)." (PMID 20019794, 2009).
infection (continued). "Levels of myeloperoxidase (MPO), which is constitutively expressed at the protein level in neutrophils and has been extensively used in previous studies to quantify neutrophil influx into tissues during infection and inflammation, were also measured." (PMID 20041174, 2009). "Lymphopenic mice developed spontaneous infections, if deficient in NADPH oxidase but not if they lacked MPO (Ostanin, Barlow, Shukla, & Grisham, 2007)." (PMID 18036868, 2008). "Neither salmeterol nor salbutamol influenced the recruitment of neutrophils to the lungs after infection with NTHi, as reflected by an unaltered number of neutrophils in BALF and in lung tissue slides, as well as by a similar rise in lung MPO concentrations in mice treated with salmeterol." (PMID 16595015, 2006). "However, in the absence of infection, the leucocytes are in a less responsive phase; thus, the oxidative burst capacity is low, resulting in a negative value compared to the MPO activity from infected samples." (PMID 41154759, 2025). "We stress that KCTD12, TF, LTF, and MPO are host-response proteins; their altered serum-exosomal levels mirror the child’s innate reaction to infection with azithromycin-resistant M. pneumoniae and do not reflect or cause the bacterial mutation that directly confers resistance." (PMID 41451080, 2025). "However, the fact that MPO was only transiently elevated at the time of the index infection indicates that MPO is unlikely to be a good marker of the sustained impact of Shigella on EE and growth." (PMID 40440324, 2025). "However, it should be noted that an operation represents a sterile inflammation and not a (bacterial) infection and that it is possible that therefore no enhanced myeloperoxidase release has been seen." (PMID 41203762, 2025). "Since fewer MPO+, CD11b+, and MHC class II+ neutrophils were found in DKK1(PKO) and MyD88(PKO) infected mice, these data suggest that neutrophil persistent activation and migration to the infection site in BALB/c mice is promoted by DKK1 release via the MyD88 signaling pathway." (PMID 40502169, 2025). "infection and high fecal myeloperoxidase to those with no Campylobacter spp." (PMID 39965021, 2025). "infection and high myeloperoxidase to those with no Campylobacter spp." (PMID 38585931, 2024). "Animal studies have revealed that NADPH oxidase, but not MPO, might be more critical for animals to fend off infections." (PMID 39199135, 2024). "Given the percentage of MPO-positive neutrophils in LRP6NKO and LRP6NKO DKK1PKO infected mice is decreased in comparison to BALB/c infected mice, these data further confirm that the interaction of DKK1 and LRP6 is essential for the migration of activated neutrophils to the infection site." (PMID 39502693, 2024). "In the patient described here, who displayed total MPO deficiency, there were no indications of increased frequency of infection, suggesting compensatory mechanisms to the specific MPO function that provides retained antimicrobial activity in the phagolysosome when MPO is absent." (PMID 37954595, 2023). "Finally, analysis of MPO+ immune cell recruitment demonstrated that GT activity of TcdB was required to elicit MPO+ immune cells to sites of infection and that GT-independent epithelial damage did not require or elicit MPO+ immune cell influx." (PMID 35176123, 2022). "However, therapeutic treatment with Ac2–26, given as a single dose at 24 h post-infection, was not sufficient to decrease MPO, CXCL1, or IL-6 levels in mice compared with untreated WT (BALB/c) animals." (PMID 36078125, 2022). "Since MPO attenuates pathogen clearance during P. yoelii nonlethal infection, it is tempting to speculate that this enzyme may inhibit parasite clearance in PM as well." (PMID 34737733, 2021).
infection (continued). "In ST2 knockout mice, MPO and EPO were decreased after infection when compared to WT animals, which might contribute to the initial resistance profile exhibited by these mice, since there are less infected granulocytes that can carry the pathogen to spread into other host cells and organs." (PMID 32353980, 2020). "Note that AGMs have relatively high levels of MPO-positive cells in the colon prior to infection, higher than in uninfected RMs (which harbor virtually no MPO-positive cells in the lamina propria), and in the range of some chronically SIV-infected RMs, as supported by quantification." (PMID 32119719, 2020). "It is not yet known in humans whether carriage or infection of S. aureus strains containing the cross-reactive 6PGD391–410 sequence promotes the induction of MPO-AAV or precipitates disease relapse." (PMID 31358739, 2019). "Additionally, we showed that the MPO-mEmerald enzyme does not disrupt neutrophil recruitment to sites of injury and infection." (PMID 31002727, 2019). "In Spotless (mpxNL144) larvae—which express a non-functional zebrafish myeloperoxidase—the MPO-mEmerald transgene does not disrupt neutrophil migration to sites of infection or inflammation, suggesting that it is a suitable line for the study of neutrophil granule function." (PMID 31002727, 2019). "In this study, noninvasive, real-time in vivo imaging of myeloperoxidase (MPO) activity, in combination with longitudinal flow cytometry, enabled the kinetic analysis of cellular populations and their activation state in the mouse ear dermis in a long-term, low-dose infection." (PMID 29097502, 2018). "Also a lack of Myeloperoxidase (MPO), an enzyme that catalyzes the synthesis of highly microbicidal hypochlorous acid, is thought to lead to increased susceptibility to infection." (PMID 30622537, 2018). "There was no relation between MPO and the development of infection on different infection sites." (PMID 28916973, 2017). "Given that neutrophil recruitment to the site of infection contributes to the clearance of P. aeruginosa, we assessed neutrophil accumulation in the lungs and BALF of CQ and saline treated mice through assaying the activity of the neutrophil specific enzyme myeloperoxidase (MPO)." (PMID 24015228, 2013). "Myeloperoxidase can form NO-derived inflammatory oxidants and it has been shown that myeloperoxidase is responsible for the majority of tissue nitrosylation in fish in the absence of infection." (PMID 24367256, 2013). "Collectively, the flow cytometry data corroborate the MPO assay results and indicate that mouse infection with wild-type P. gingivalis, but not with the rbr− strain, triggers an increase in the number of circulating neutrophils and boosts the systemic activation of these cells." (PMID 16895445, 2006). "Furthermore, AAV9shRamp1 infection led to extensive inflammatory cell infiltration and a dispersed distribution of CitH3+MPO+ NETs at injured sites, neither of which could be effectively controlled by the exogenous addition of CGRP." (PMID 41554692, 2026). "Interestingly, the levels of MPO, CD11b and MHC class II positive PMNs of LRP6NKO and LRP6NKO DKK1PKO mice were comparable and were not significantly different from naïve mice, suggesting that the activation of PMNs upon infection is primarily through the LRP6 pathway." (PMID 39502693, 2024). "On the other hand, the interactions between MPO and the identified proteinous fungal partners did not influence the MPO’s enzymatic properties, meaning that at the place of infection MPO could still be responsible for the conversion of hydrogen peroxide to hypochlorite used for microbe inactivation." (PMID 34685715, 2021). "In addition, we detected myeloperoxidase (MPO), which was released from polymorphonuclear neutrophils (PMN) in the lung tissue in response to exposure to various pulmonary insults and may serve as an indicator of the degree of infection." (PMID 34768852, 2021).
infection (continued). "However, neutrophil depletion did not completely abolish airway MPO during the infection, suggesting there may be an alternative cellular source of this mediator." (PMID 31358860, 2019). "Furthermore, to assess the absence of significant differences in MPO and elastase production between strains within the first hours of infection, a kinetics of released MPO and elastase activities (2, 4, 6, and 18 h) was performed in case of three of the 14 donors." (PMID 31134162, 2019). "However, any unusual expression and release of MPO from activated neutrophils intensifies the inflammation and tissue damage and may result in several other diseases, even in the absence of infection." (PMID 29669993, 2018). "NE and MPO expressed on DNA fibers stimulated by F protein could exacerbate lung pathology induced by RSV infection, through the destruction of connective tissue, degradation of endothelial cell matrix heparan sulfate proteoglycan, resulting in post infection tissue injury." (PMID 25856628, 2015). "While the actual levels of HOCl that MPO generates in the airways is not known, it is conceivable that in isolated microenvironments the concentration of HOCl could easily reach at least 750 μM during infection or disease." (PMID 20799947, 2010). "In the current study, supplementing glutamine without or with omega-3 had decreased the intestinal MPO, NO and NOS after infection with Eimeria spp." (PMID 38961536, 2024). "Treatment began 18 h after infection, and when GLY was combined with the moxifloxacin, its pH did not affect reduction of viable plate count or MPO." (PMID 35127554, 2021). "After KEI 1025 infection, none of the GLY vs. PBS-treated corneas perforated; GLY treatment also decreased plate count (neutral pH more effective) and reduced MPO and several cytokines." (PMID 35127554, 2021). "While both proteins were highly present after infection, neither was dependent on the presence of TNC (P = 0.96 and P = 0.66 for myeloperoxidase and neutrophil elastase, respectively)." (PMID 34319124, 2021). "We confirmed that mock infection did not induce the secretion of MMP-9, MPO or NE into the airways or the upregulation of cell surface activation marker CD64 at any time point." (PMID 31358860, 2019). "Myeloperoxidase (MPO) activity, an approximate measure of PMN infiltration, was transiently higher in the PVL group at 3 h post infection, but was not significant at any other time points." (PMID 26618545, 2015). "Serial infection with NU14 or ΔwaaL also induced transient increases in urinary MPO, yet MPO was not significantly different between strains at any time point or between any single infection and serial infection." (PMID 22899994, 2012). "Among the non-specific immune indicators, such as lysozyme, myeloperoxidase, and alkaline phosphatase activities, LZM, a non-specific protein-based defense factor, plays an important role in aquatic animal resistance to pathogen infection." (PMID 39728130, 2024). "However, neither MPO-ANCA nor PR3-ANCA affected the three poor outcomes (cumulative survival rate, mechanical ventilator-free survival rate, and severe infection-free survival rate)." (PMID 35887916, 2022). "Immunohistologic examination at day 28 post-aerosol infection revealed that F4/80+ macrophages, CD3+, CD4+ and CD8+ cells localized in perigonadal fat, whereas no positive staining for myeloperoxidase (MPO) abundantly expressed in neutrophils, or for the pan B cell marker B220 was observed." (PMID 29040326, 2017). "Furthermore, as measured by tissue MPO activity, PVL induced increased neutrophil infiltration in CD1 and (to a lesser extent) in BALB/c mice at 3 h post-infection, but not in SKH1 and C57BL/6 mice." (PMID 19633710, 2009). "However Myeloperoxidase may not be required with all stimuli, since MPO was shown to be dispensable for NET induction in infections with Pseudomonas aeruginosa or Staphylococcus aureus." (PMID 30016370, 2018).